ABHD14A-ACY1 (ABHD14A-ACY1 readthrough)
Gene: Protein-coding gene on chromosome 3 (51,974,706 to 51,989,183, forward strand). Ensembl gene ENSG00000114786.
Genetic constraint (gnomAD): Loss-of-function variants: 49 observed, 65.5 expected, observed/expected ratio (o/e) 0.75, 90% interval 0.59 to 0.95. The upper end of that interval is the gene's LOEUF score, 0.95, which puts it in group 4 of 6, group 1 being the genes least tolerant of losing a copy. Missense variants: 603 observed, 669.1 expected, observed/expected ratio (o/e) 0.9, 90% interval 0.84 to 0.96. Synonymous variants: 238 observed, 263.21 expected, observed/expected ratio (o/e) 0.9, 90% interval 0.81 to 1.01.